NGF (nerve growth factor)
Diseases named in the same sentence as NGF in open-access papers (continued):
Sharing a sentence is not in itself a finding about the gene and the disease.
diabetes (continued). "In this context, it is relevant that we found ed-NGF treatment also resulted in a decrease in microvessel fragmentation in STZ, and reduced expression of Rock1, a marker of endothelial cell dysfunction, as well as Müller cells in diabetic retina." (PMID 36291113, 2022). "NGF levels in the dorsal root ganglion (DRG) and dorsal horn in rat models, when explored, were discovered to drop in the DRG 1 week after diabetes induction and in the dorsal horn 2 weeks after diabetes induction." (PMID 35127954, 2022). "NGF-driven re-activation of the insulin pathway through disinhibition and tyrosine phosphorylation of IRS1, a primary gatekeeper in insulin signaling, is a potential novel strategy to slow cognitive decline in AD and diabetes-related brain insulin resistance." (PMID 29736736, 2019). "Mice transplanted with NGF-treated WT pDCs displayed a delayed increase of blood glucose levels and later diabetes onset compared to mice transplanted with WT pDCs without preceding NGF treatment." (PMID 28861085, 2017). "Two out of 11 (~18%) mice transplanted with NGF-treated pDCs developed no diabetes within 51 days of observation, while all mice transplanted with WT pDCs without preceding NGF treatment developed diabetes within 44 days." (PMID 28861085, 2017). "The median diabetes-free incidence was prolonged by 7.5 days upon pre-treatment of transplanted WT pDCs with NGF (with NGF: 37 days; without NGF: 29.5 days; p = 0.08)." (PMID 28861085, 2017). "Diabetes-induced proNGF/NGF imbalance was attributed to the reduction in expression and activity of MMP-7, the enzyme that cleaves proNGF to form mature NGF resulting in accumulation of proNGF and decreases in NGF levels in the retina." (PMID 26807305, 2015). "In the STZ model of experimental diabetes it has been reported that VEGF expression increased in DRG and sciatic nerves and that insulin and/or nerve growth factor administration could prevent it." (PMID 25268360, 2014). "Nerve growth factor (NGF) was identified as the most over-represented target in this subset when compared to the full ROS-diabetes set; however, NGF did not have statistical significance (BH adjusted p-value = 0.06)." (PMID 20979611, 2010). "However, ST-induced diabetic rats treated with NGF eye drops showed a non-significant trend toward protecting ganglion cells from diabetes-induced degeneration." (PMID 39473506, 2024). "In addition, intracavernous injection of ADSCs-derived microtissues improves erectile function in STZ-induced diabetic rats via expressing vascular endothelial growth factor (VEGF), nerve growth factor (NGF), and tumor necrosis factor-stimulated gene-6 (TSG-6)." (PMID 36923224, 2023). "Similarly, NGF levels in murine WAT and BAT increase during stress and diabetes." (PMID 36768281, 2023). "Thus, targeting the NGF/VEGF interaction system should be also regarded as a potential new strategy for anti-angiogenic therapy against cancer as well as for other angiogenesis-dependent diseases, such as diabetes, and arthritis." (PMID 23190582, 2012). "However, the role of NGF in diabetes-induced CKD is not very clear." (PMID 35874807, 2022). "A preclinical study evaluated whether NGF gene transfer could mitigate the onset and progression of diabetic cardiomyopathy (DCM) in a murine model of STZ-induced diabetes, compared to non-diabetic controls." (PMID 41471293, 2025). "More specifically we looked at whether diabetes adversely affects retinal neurons due to lack of neurotrophic levels, such as in the case of insulin, PEDF, and BDNF, and/or due to lack of activity, such as in the case of VEGF and NGF." (PMID 21293735, 2011).
neuroblastoma (101 papers, 1996 to 2025). Neuroblastoma (NB) is the most common solid, extracranial childhood tumor. "The withdrawal of NGF from terminally differentiated SH-SY5Y neuroblastoma cell cultures causes apoptotic cell death." (PMID 41189817, 2025). "On the other hand, NGF deficiency-dependent apoptotic pathways remain to be investigated in spontaneous regression of stage 4S neuroblastoma." (PMID 41189817, 2025). "DMSO (dimethyl sulfoxide), NGF (nerve growth factor) or RA-induced differentiation of neuroblastoma cells is associated with increased c-Jun expression." (PMID 40149013, 2025). "While NGF exerts trophic effects on normal cells, dysregulated NGF signaling pathways have been implicated in the pathogenesis and progression of pediatric malignancies, including neuroblastoma and retinoblastoma." (PMID 39056738, 2024). "Studies have shown that PCD induced by NGF deficiency in NGF-dependent human neuroblastoma cells, UNC5D emerges as a key player in this intricate regulatory network." (PMID 39186800, 2024). "One of the candidate key mechanisms underlying tumor regression is the nerve growth factor (NGF) dependency of neuroblastoma cells." (PMID 34796286, 2021). "Abnormal NGF signaling has been linked to nervous system tumors such as neuroblastoma, medulloblastoma, and pheochromocytoma." (PMID 26885691, 2016). "In SHSY5Y neuroblastoma cells, huperzine A treatment reversed the reduction in NGF level that was caused by H2O2-induced oxidative stress; this effect was due to the activation of p75NTR and TrkA receptors and the upstream MAP/ERK signaling pathway." (PMID 26075266, 2015). "Favourable neuroblastomas often express high levels of trkA mRNA, encoding the tyrosine kinase receptor for nerve growth factor." (PMID 8795581, 1996). "Furthermore, this signature has potential to be a target for treatment and a strong indicator of gene expression changes underlying NGF independent NTRK1 activation promoting differentiation of neuroblastoma cells." (PMID 38398114, 2024). "Finally, neurotrophic tyrosine kinase 1 (NTRK1, TrkA), is a well-known neuroblastoma antigen that binds nerve growth factor, and whose expression has been associated with a number of human cancers, often being discovered as an oncogenic fusion protein." (PMID 28871274, 2017). "Moreover, PHLDA1 downregulation was shown to affect differentiation-associated transcripts such as ID1, ID2 (encoding inhibitors of differentiation 1, 2), NTRK1, NTRK2 (encoding tropomyosin receptor A, B), and NGF (encoding nerve growth factor) in IMR-32 neuroblastoma cells." (PMID 39630301, 2025). "Schwann cells then secrete NGF that promotes the differentiation of neuroblastoma cells with NTRK1 expression." (PMID 41189817, 2025). "Apoptosis, differentiation, T cell-mediated immunity, nerve growth factor (NGF) deprivation, impaired DNA repair, epigenetic control, and telomere shortening are among the main potential mechanisms of spontaneous regression in neuroblastoma." (PMID 41189817, 2025). "Here, we describe the ability of erdosteine, a thiolic compound classified as a mucolytic agent, to bind to the TrkA receptor sequence in silico and its in vitro effects on TrkA activation induced by NGF in cultured human neuroblastoma cells." (PMID 40362318, 2025). "The MAPK/ERK pathway is reportedly activated by ectopic NGF secretion in neuroblastoma, breast cancer, colon cancer and pancreatic ductal adenocarcinoma (PDAC)." (PMID 40783715, 2025). "The potential mechanisms of spontaneous regression in neuroblastoma are involved in apoptosis, differentiation, impaired DNA repair, adaptive T cell-mediated immunity, NGF deprivation, telomere shortening, and epigenetic control." (PMID 41189817, 2025). "The JAK/STAT and PI3K/AKT pathways can also be activated by NGF in the context of glioma and neuroblastoma." (PMID 40783715, 2025). "BDNF and NGF production activity is related to the increased histone H3 and H4 acetylation in a mouse neuroblastoma cell line (Neuro2A)." (PMID 39519391, 2024).
neuroblastoma (continued). "In the present study, we used four neuroblastoma cell lines with inducible NTRK1 expression to study dynamics in NTRK1 downstream signaling induced by NGF treatment." (PMID 34771457, 2021). "The inducible expression of NTRK1/TrkA and its activation via NGF were realized and validated in four established human neuroblastoma cell lines, NGP, IMR5, SKNAS and SH-SY5Y." (PMID 34771457, 2021). "Using fluorescence microscopy, we demonstrated that NGF-induced NTRK1 signaling induces the accumulation of LMNA inside nuclear foci in all neuroblastoma cell lines that were analyzed." (PMID 34771457, 2021). "NTRK1 and its activation by nerve growth factor (NGF) have been shown to induce differentiation and increase the immunogenicity of human neuroblastoma cells." (PMID 34771457, 2021). "GM1 acts as a bridge able to increase and stabilize the interactions of NGF with its high affinity receptor TrkA, which promotes neurite formation in murine neuroblastoma (Neuro2a) cells." (PMID 32214122, 2020). "Differences in gene expression profile amongst diverse subclones of SH-SY5Y neuroblastoma cells have been determined to play significant roles in modulating neurite outgrowth responses to NGF." (PMID 30687846, 2018). "For example, TRKA expression in neuroblastoma confers a good prognosis via a potential tumor-suppressing role for TRKA and NGF signaling in neuroblastoma cells, resulting in differentiation, growth arrest, and angiogenesis inhibition." (PMID 29617282, 2018). "KIF1Bβ has been reported as a potential tumour suppressor in neuroblastoma with respect to its crucial role in mediating developmental culling of NGF-deprived neuroblasts during NGF signalling phase of sympathetic nervous system development." (PMID 29203804, 2017). "For instance, NGF/TrkA induces differentiation, apoptosis, and growth inhibition in neuroblastoma and medulloblastoma, and high expression of TrkA is considered a favorable prognostic indicator in neuroblastoma." (PMID 28557340, 2017). "One of the mechanisms that give rise to neuroblastoma is the failure of neural progenitors to undergo apoptosis via an EglN3-dependent pathway when nerve growth factor (NGF) becomes limiting during development." (PMID 27097110, 2016). "In conclusion, we report a novel important pro-apoptotic immunological dimension to the interaction between NGF and the TrkA receptor in sensitizing neuroblastoma cells to TRAIL-induced apoptosis." (PMID 27551499, 2016). "Expression of Kidins220 has also been reported in neuroblastoma tumours, where it stabilizes nerve growth factor-induced survival signalling through MAPK/ERK signalling." (PMID 27329728, 2016). "Uridine (100 μM) was found to increase the percentage of neurite-bearing cells of differentiating neuroblastoma (N2a) cells by 43.1±0.5%, which was 1.8-fold higher than NGF (50 ng/mL)-treated cells." (PMID 26565787, 2015). "It has previously been reported that berberine attenuates diabetic neuropathy in neuroblastoma cells by inducing hemeoxygenase-1 and NGF expression." (PMID 26075266, 2015). "Schwann cells were previously reported to express and secrete the NTRK1-specific ligand, NGF, which lead to peripheral nerve regeneration and axonal myelination as well as to neuroblastoma cell differentiation." (PMID 25361003, 2014). "Treatment with NGF also induces a similar nuclear accumulation of FGFR1 in human neuroblastoma cells." (PMID 23874817, 2013). "Isoquercitrin-induced neurite formation was significantly higher compared to conditions such as DMSO-low serum, serum free medium, and Nerve Growth Factor (NGF) which are reported to induce neural differentiation of neuroblastoma cells." (PMID 23209630, 2012). "The experimental model was the mouse PC12 neuroblastoma cell line which can be induced to differentiate into neurons in the presence of NGF (nerve growth factor)." (PMID 21176150, 2010).
neuroblastoma (continued). "βCstF-64 mRNA was detected in CA77 (lane 5), undifferentiated and NGF-differentiated PC-12 cell lines (lanes 6 and 7), TT (lane 2), and SK neuroblastoma cell lines (lane 3)." (PMID 19284619, 2009). "NTRK1 may play a pivotal role in spontaneous regression of stage 4S neuroblastoma through both the induction of the NGF-dependent neuronal differentiation and the enhancement of the immune response." (PMID 41189817, 2025). "Furthermore, incubation with conditioned media from IPA-treated microglia restored BDNF and nerve growth factor (NGF) expression in neuroblastoma cells inhibited by LPS." (PMID 40942152, 2025). "We have previously identified a role for Cbl-b as a negative regulator of NGF-TrkA signaling in neuroblastoma cells and found that depletion of Cbl and Cbl-b was associated with induction of neurite outgrowth, a morphological marker of neuroblastoma differentiation." (PMID 33889818, 2021). "Most previous studies of neuroprotection have used rat pheochromocytoma 12 (PC12) and human SH-SY5Y neuroblastoma cell lines, since these cell lines differentiate into neuronal cells with elongated neurites upon treatment with nerve growth factor (NGF) or retinoic acid." (PMID 30042342, 2018). "Additionally, mPRβ mRNA was significantly increased in the NGF-induced neuronal human neuroblastoma cell lines SH-SY5Y as well." (PMID 28701790, 2017). "Indeed, the experimental evidence that NGF exposure induces differentiation rather than proliferation in cancer cell line (pheochromocytoma, glioma, neuroblastoma and pancreatic beta cells) argues against the pro-cancer role of NGF." (PMID 27439311, 2016). "This suggests that loss of KIF1Bβ may impair NGF-deprived apoptosis due to mislocalization of RHA and predispose to neuroblastoma formation." (PMID 26885691, 2016). "NGF signalling is a predominant signalling pathway in neuroblastoma." (PMID 26010602, 2015). "Since SH-SY5Y cells are derived from a neuroblastoma, the neuronal differentiation of monolayer cultures is poorly developed and has to be promoted via retinoic acid, staurosporine or neurotrophic factors as NGF or BDNF." (PMID 23145103, 2012). "However, the exact role of the AXL receptor, which functions in the NGF-dependent neuronal differentiation pathway, remains unknown in stage 4S neuroblastoma." (PMID 41189817, 2025). "Intriguingly, primary neuroblastoma cells with high TrkA expression display differentiation with neurite outgrowth in the presence of NGF but undergo apoptosis in the absence of NGF, giving insight into the mechanisms underlying spontaneous regression of neuroblastomas." (PMID 36831211, 2023). "For example, CASZ1 suppresses NB partially due to upregulation of NGFR, which encodes a Fas/TNF-R family receptor that mediates apoptosis of neuroblastoma cells in the presence of nerve growth factor (NGF)." (PMID 37509718, 2023). "Hence, these in vitro culture conditions appear to recapitulate the behavior of TRKA-expressing neuroblastomas in patients with neuronal differentiation or spontaneous regression (apoptosis), depending on the presence or absence, respectively, of NGF in the microenvironment." (PMID 34796286, 2021). "ND7/23 cells are created by fusing N18tg2 mouse neuroblastoma cells and neonatal rat dorsal root ganglion cells, and they are often used as an immortalized proxy for peripheral [including corneal] sensory neurons because they are readily differentiated by addition of nerve growth factor (NGF)." (PMID 33232327, 2020). "Further studies revealed that nerve growth factor (NGF) and epidermal growth factor-like protein 8 (EGFL8) are able to induce neuroblastoma differentiation and hence inhibit tumor proliferation." (PMID 39199637, 2024).
neuroblastoma (continued). "Given that endogenous FFAR3 expression in Neuro-2A cells is equivocal (very low at best), we transfected these neuroblastoma cells to express human FFAR3, prior to their NGF-elicited neuronal differentiation." (PMID 35628613, 2022). "Of these, four peptides induced neurite outgrowth, two peptides inhibited nerve growth factor (NGF)-induced neurite outgrowth and eight peptides induced neurite outgrowth in human SH-SY5Y neuroblastoma cells." (PMID 36296244, 2022). "VGF is known to be induced by neurotrophic factors (e.g. BDNF and NGF) and also shows up-regulation after RET activation in neuroblastoma cells." (PMID 35012575, 2022). "Human neuroblastoma SH-SY5Y cells incubated with bacteria-free mouse colonic supernatant, 5-HT, nerve growth factor, or brain-derived neurotrophic factor exhibited nerve fibre elongation, which was inhibited by 5-HT7 antagonists." (PMID 35585132, 2022). "Higgins and colleagues have previously demonstrated using a human neuroblastoma cell line (SH-SY5Y), that seven days of continuous progressive mechanical stimuli promote differentiation and neurite outgrowth similar to NGF administration." (PMID 34168249, 2021). "Similar observations were made in PC12W cells differentiated by nerve growth factor (NGF) and in undifferentiated NG108-15 cells (mouse neuroblastoma x rat glioma hybrid cell line)." (PMID 33668331, 2021). "Recently, hNGF1–14 has been prospected to mimic the whole NGF protein by activating TrkA and its downstream pathway in PC12 and SH-SY5Y neuroblastoma cell lines, mainly in presence of Cu2+ and Zn2+ metals." (PMID 32024191, 2020). "In contrast to tumor-suppressing role of full-length TrkA, a constitutively-active TrkAIII splice form in primary neuroblastomas and in SH-SY5Y cell line, antagonizes NGF/TrkA signalling and promotes tumor progression." (PMID 30034627, 2018). "The neuroblastoma cell line SH‐SY5Y was transfected with wild‐type TRKA‐GFP, the mutants p.G517E, p.L657P, p.C752S, p.C763S and empty vector and treated with NGF over 9 days." (PMID 27676246, 2017). "Using the human neuroblastoma SH-SY5Y cell line, we have demonstrated that RA and NGF increase both endogenous VGF mRNA expression and VGF promoter activity." (PMID 26643910, 2016). "We next applied KSR-LIVE to another recently published temporal phosphoproteomics dataset–a time-course of NGF stimulation in a human neuroblastoma cell line (SH-SY5Y), hereafter referred to as ‘NGF Dataset’." (PMID 27336693, 2016). "GAP-43 overexpression strikingly potentiated the action of NGF on neurite initiation and regeneration in PC12 cells while GAP-43 inhibition prevented the neuritogenesis of neuroblastoma cells." (PMID 26840295, 2016). "ERK activation has been shown to correlate with nerve growth factor-induced neuroblastoma cell differentiation, suggesting a role for the RAS/MAPK pathway in neuroblastoma differentiation." (PMID 27014418, 2016). "Our study provides strong evidence that NTRK1-expressing neuroblastoma cells both attract and stimulate the proliferation of adjacent Schwann cells by secreting NRG1, which in turn leads to NGF-mediated differentiation of neuroblastic cells." (PMID 25361003, 2014). "The present study verifies that the nuclear accumulation of FGFR1 constitutes a common response to NGF in both neural crest derived rat PC12 and human neuroblastoma cells." (PMID 23874817, 2013). "We and others have reported that early growth response-1 (Egr-1), an important transcription factor that regulates p35 expression, is rapidly upregulated after NGF or TNF-α treatment in PC12 cells, and after TGF-β1 treatment in B104 rat neuroblastoma cells." (PMID 23668392, 2013). "Egr1 is one possible candidate, since in PC12 cells NGF induces Egr1 downstream of ERK and EGR1 is required in the differentiation of neuroblastoma cells." (PMID 21298006, 2011).